ENSG00000111780 (novel protein)
Gene: Protein-coding gene on chromosome 12 (120,438,198 to 120,460,006, forward strand). Ensembl gene ENSG00000111780.
Genetic constraint (gnomAD): Loss-of-function variants: 12 observed, 14.56 expected, observed/expected ratio (o/e) 0.82, 90% interval 0.53 to 1.33. Missense variants: 195 observed, 214.86 expected, observed/expected ratio (o/e) 0.91, 90% interval 0.81 to 1.02. Synonymous variants: 100 observed, 92.81 expected, observed/expected ratio (o/e) 1.08, 90% interval 0.92 to 1.27.